TUBB2B (tubulin beta 2B class IIb)
Diseases named in the same sentence as TUBB2B in open-access papers (continued):
Sharing a sentence is not in itself a finding about the gene and the disease.
cortical dysplasia (4 papers, 2014 to 2022). "Defects of TUBB2A and TUBB2B genes are linked to cortical dysplasia in combination with other brain malformations type 5 and type 7, respectively." (PMID 35911393, 2022).
epilepsy (4 papers, 2019 to 2022). A brain disorder characterized by episodes of abnormally increased neuronal discharge resulting in transient episodes of sensory or motor neurological dysfunction, or psychic dysfunction. "Individuals generally showed a broad range of focal and generalized semiologies that occurred similarly in TUBA1A- and TUBB2B-associated epilepsy." (PMID 33082561, 2021). "In the TUBB2B cohort, epilepsy was associated with complete agenesis of the CC and brainstem hypoplasia." (PMID 33082561, 2021). "Among patients described in literature carrying mutations in TUBA1A gene, epilepsy was reported in 28% (44/155), while it was described in 49% (19/39) of TUBB2B and in 5% (3/62) of TUBB3 mutated patients." (PMID 31269740, 2019). "Among the α- and β-tubulin genes, TUBA1A (28% of the cases) and TUBB2B gene (49%) are those more frequently associated with epilepsy." (PMID 31269740, 2019). "Among them, IPA revealed that 5 genes (Gfap, Gmppa, Tubb2b, SLC22a8 and Plxnb3) were related to epilepsy or neurodevelopmental disorders." (PMID 35474103, 2022). "In both cohorts, infantile onset of epilepsy was seen in the majority of cases (84.6% vs. 78.6%) indicating a broader range of age at seizure onset in TUBB2B cases." (PMID 33082561, 2021). "Interestingly, 5 genes (Gfap, Gmppa, Tubb2b, SLC22a8 and Plxnb3) among the DEGs are known to be related to epilepsy or neurodevelopmental disorders." (PMID 35474103, 2022). "EEG and clinical data of six epileptic patients from a cohort of 15 patients carrying mutations in TUBA1A, TUBB2B and TUBB3 tubulin genes are analyzed as well as a literature review on the role of these genes and epilepsy is reported with the aim to define a specific associated epileptic pattern." (PMID 31269740, 2019). "Mutations in TUBA1A (60%) and TUBB2B (74%) and TUBB3 (25%) genes are associated with epilepsy." (PMID 31269740, 2019). "Epilepsy was common in both cohorts: 65.9% (TUBA1A) and 54.8% (TUBB2B) of individuals developed seizures during the observation period." (PMID 33082561, 2021). "Incidence of mutations associated with epilepsy is not significantly different among the tubulin domains for TUBA1A and TUBB2B genes, while in the TUBB3 gene, the C-domain does not show mutations related to epileptic features." (PMID 31269740, 2019). "Clinical and EEG data: six out of 15 patients presented epileptic seizures (40%) (three with TUBA1A gene mutation and three with TUBB2B gene mutation; none TUBB3 carrying gene mutation showed epilepsy)." (PMID 31269740, 2019).
microlissencephaly (4 papers, 2014 to 2024). Microlissencephaly describes a heterogenous group of a rare cortical malformations characterized by lissencephaly in combination with severe congenital microcephaly, presenting with spasticity, severe developmental delay, and seizures and with survival varying from days to years. "In this cohort, TUBA1A mutations represent the major cause of microlissencephaly, although TUBB2B and TUBB3 mutations may also be found." (PMID 25059107, 2014). "Moreover, we report for the first time, one TUBB2B mutation responsible for microlissencephaly." (PMID 25059107, 2014). "Because of the potential implications for the genetic screening, our data together with these observations imply that microlissencephaly must be distinguished from LCH, the former being related to either TUBA1A, TUBB2B or TUBB3 mutations, while the latter strongly related to TUBA1A mutations." (PMID 25059107, 2014).
breast carcinoma (3 papers, 2023 to 2025). "We also find that upregulation of TUBB2B is associated with poor prognosis in breast cancer patients." (PMID 39962586, 2025). "We also observed an association between increased TUBB2B expression and unfavorable overall survival (OS) as well as distant metastasis-free survival (DMFS) outcomes in breast cancer patients." (PMID 39962586, 2025). "In line with previous findings that TUBB2B was minimally expressed in normal breast epithelium, we found it to be expressed at a low level in luminal breast cancer MCF7 cells and normal HMEC." (PMID 39962586, 2025). "To explore the function of TUBB2B in TNBC, we generated a panel of breast cancer lines with TUBB2B knockdown." (PMID 39962586, 2025). "In this study, we uncovered an oncogenic role of TUBB2B in breast cancer by observing that depletion of TUBB2B induces TNBC cell apoptosis and inhibits tumor maintenance and brain metastasis colonization in preclinical models." (PMID 39962586, 2025). "However, the functional role of TUBB2B in the pathogenesis of breast cancer or metastasis has yet to be studied." (PMID 39962586, 2025). "TUBB2B overexpression was also found to be a predictor of poor DMFS in breast cancer patients." (PMID 39962586, 2025). "Although little is known about the functional participation of the TUBB2B subtype in breast cancer, including endocrine therapy-resistant ER-positive breast cancer, TUBB2B can function as an oncogene in hepatocellular carcinoma and plays a role in promoting cell proliferation." (PMID 37754248, 2023). "We demonstrated that TUBB2B is overexpressed in approximately 26% of TNBC cases, and its upregulation predicts poor DMFS in breast cancer patients." (PMID 39962586, 2025). "Based on bioinformatics analysis of public datasets as well as our in-house RNAscope data, TUBB2B is upregulated in brain metastasis, and its high expression predicts poorer DMFS in breast cancer patients." (PMID 39962586, 2025). "In breast cancer patients, TUBB2B, but not other β-tubulin isoforms, is upregulated in brain metastases compared to lung and bone metastases (GSE14017)." (PMID 39962586, 2025). "In their study, western blotting showed that the expression of PER1 and PER2 decreased in the rhythm group, whereas the expression of breast carcinoma amplified sequence 4 (BCAS4), tubulin beta-2B chain (TUBB2B), and Roof Plate-Specific Spondin-4 (RSPO4) increased in the breast cancer group." (PMID 38074657, 2023). "Although overexpression of TUBB2B has been found in endocrine therapy-resistant breast cancer and brain metastases of TNBC patients, its functional role in breast cancer or metastasis has not been identified." (PMID 39962586, 2025).
endometrial cancer (3 papers, 2021 to 2025). Primary or metastatic malignant neoplasm involving the endometrium (mucous membrane that lines the endometrial cavity). "Higher TUBB2B expression in a subpopulation of endometrial cancer patients is associated with poorer prognosis." (PMID 39962586, 2025). "Rhythm-related factors PER1, TUBB2B, and tumor immune factors can regulate the pathogenesis and progression of endometrial cancer." (PMID 34220965, 2021).
prostate carcinoma (3 papers, 2022 to 2023). A carcinoma that arises from epithelial cells of the prostate gland. "TUBB2B has also been associated with DTX resistance in prostate cancer." (PMID 37476073, 2023). "Contrastingly, TUBB2B was upregulated in both taxane-resistant prostate cancer cell lines, approximately 12-fold in DUTXR and approximately 43-fold in PC-3TXR." (PMID 37476073, 2023). "We also identified C1orf116, TUBB2B are common genes in taxane-resistant prostate cancer subtypes." (PMID 37476073, 2023).
Ataxia (2 papers, 2022 to 2025). Ataxia refers to impaired coordination of voluntary muscle movement. "Exception is confined to a recessive disorder, Uner Tan syndrome, also known as cerebellar ataxia, impaired intellectual development, and disequilibrium syndrome (CAMRQ, MIM #224050), which has been linked to the homozygous pathogenic missense variant (p.Arg390Gln) in TUBB2B in one single family." (PMID 41153399, 2025).
congenital fibrosis of the extraocular muscles (2 papers, 2023 to 2025). "While the majority of TUBB2B pathogenic variants have been linked to isolated CDCBM7, only one family with CDCBM7 and congenital fibrosis of the extraocular muscles (CFEOM) has been reported so far." (PMID 41153399, 2025). "Congenital fibrosis of the extraocular muscles (CFEOM) affects cranial nerves 3 and 4 and is caused by autosomal dominant missense variants in KIF21A, TUBB3, TUBB2B or TUBA1A or autosomal recessive variants in PHOX2A." (PMID 38500555, 2023). "TUBB2B and TUBB3-related β-tubulinopathies can also present as disorders of axon growth and guidance, causing additional anomalies in axons innervating the oculomotor muscles, resulting in an eye-movement disorder termed as congenital fibrosis of the extraocular muscles (CFEOM; MIM: PS135700)." (PMID 41153399, 2025).
Alzheimer disease (1 paper, 2025). A progressive, neurodegenerative disease characterized by loss of function and death of nerve cells in several areas of the brain leading to loss of cognitive function such as memory and language. "Neurological diseases due to the overexpression of TUBB2B have not been reported, but a recent study showed that TUBB2B is upregulated in astrocytes of patients with Alzheimer’s disease (AD)." (PMID 39962586, 2025).
Arthritis (1 paper, 2018). Inflammation of a joint. "Nevertheless, some of these genes participate in nervous system development (CLSTN2, TUBB2B), inflammation including arthritis (AOC3) and stress-induced responses (C10orf10), making them promising molecular candidates in OA-driven pain." (PMID 29973527, 2018).
asthma (1 paper, 2021). "The GM13-up related to interleukin-26 (IL26, PIK3R5, and LRRC2) was much higher expressed in severe individuals while the GM12-down module related to the nervous system (10%, p = 1.77E-04, i.e., TUBB2B, SPOCK1, and ASCL1) was much lower expressed in severe asthma individuals." (PMID 34759961, 2021).
brain tumor (1 paper, 2025). "In the brain tumor microenvironment, TUBB2B activates astrocytes, which in turn upregulate expression of TUBB2B in TNBC cells." (PMID 39962586, 2025).
breast tumor (1 paper, 2025). "RNAscope in situ hybridization was used to examine TUBB2B expression in clinical breast tumor samples." (PMID 39962586, 2025). "Our findings suggest that targeting TUBB2B therapeutically would be promising for TNBC patients, as it has minimal effect on normal breast cells or luminal breast tumor cells upon TUBB2B silencing." (PMID 39962586, 2025). "Using clinically annotated gene expression datasets (n = 310, TCGA;), we found that TUBB2B mRNA is upregulated in 26% of TNBC cases, compared to 3% and 1.3% in luminal and HER2 + breast tumors, respectively." (PMID 39962586, 2025).
glioma (1 paper, 2025). A benign or malignant brain and spinal cord tumor that arises from glial cells (astrocytes, oligodendrocytes, ependymal cells). "The markers for this population are largely expressed only in glioma cells (e.g., NFIB, MAP1B, TUBB2B) and they express low levels or have no expression of myeloid/immune markers (CD74, APOE, HLA genes, and CD45)." (PMID 40588233, 2025).
heart failure (1 paper, 2016). Inability of the heart to pump blood at an adequate rate to meet tissue metabolic requirements. "Supporting the notion that the tubulin network is distorted in heart failure cells, mRNA expression analysis by qPCR confirmed an overall increase in the expression of α1A-tubulin (TUBA1A), β2B-tubulin (TUBB2B), β3-tubulin (TUBB3), γ-1tubulin (TUBG1), and microtubule-associated proteins (MAP4)." (PMID 26725114, 2016).
juvenile-onset dystonia (1 paper, 2025). "Of note, the spectrum of clinical presentations caused by pathogenic TUBB2B variants appears to be broader, ranging from very mild phenotypes to severe ones, including juvenile-onset dystonia as major signs with wide inter- and intra-familial variability reported." (PMID 41153399, 2025).
kidney cancer (1 paper, 2022). Primary or metastatic malignant neoplasm involving the kidney. "TUBB2B has been shown to participate in the construction of a prognostic model of kidney cancer." (PMID 36189312, 2022).
lung carcinoma (1 paper, 2024). "A network of interactions between proteins TUBB2B, MAPK7, TUBAL3, MAP2K5, and GJA1 (Cx43) suggests that reduced expression of MAPK and tubulin genes could be responsible for the attenuation of the gap junction pathway and insensitivity of lung cancer cells to cisplatin." (PMID 38351531, 2024).
lymph node metastasis (1 paper, 2023). "Three survival-related genes (TMEM59L, CLCA1, and TUBB2B) were associated with the lymph node metastasis and survival time of patients." (PMID 37719786, 2023). "CLCA1 protein expression was lower in the lymph node metastasis group, while the TMEM59L and TUBB2B were higher in the lymph node metastasis group." (PMID 37719786, 2023). "In light of these observations and analysis in TCGA data, we hypothesized that TMEM59L, CLCA1, and TUBB2B may be the disease markers for lymph node metastasis of CRC." (PMID 37719786, 2023). "A uni-factor COX analysis was performed on the characteristic genes of lymph node metastasis, and three survival-related genes (p < 0.05) were obtained, including TMEM59L, CLCA1, and TUBB2B." (PMID 37719786, 2023). "In this study, nine lymph node metastasis genes were analyzed via uni-factor COX regression, and three survival-related genes (TMEM59L, CLCA1, and TUBB2B) were ultimately identified." (PMID 37719786, 2023).
memory impairment (1 paper, 2023). "In the present study, we found that Sal intervention reduced hippocampal Tubb2b gene expression, which provides an idea to study memory impairment from a genetic perspective." (PMID 37362918, 2023).
neuroendocrine tumors (1 paper, 2022). "To identify neuroendocrine tumors in our cohort we have added various neuronal markers (i.e., NESTIN, TUBB2B, PEG10) to our gene classifier." (PMID 36230835, 2022).
osteoporosis (1 paper, 2022). A condition of reduced bone mass, with decreased cortical thickness and a decrease in the number and size of the trabeculae of cancellous bone (but normal chemical composition), resulting in increased fracture incidence. "After construction the miRNA-gene interaction network, we identified 6 hub miRNAs (hsa-miR-18b-3p, hsa-miR-361-3p, hsa-miR-484, hsa-miR-519e-5p, hsa-miR-940, and hsa-miR-1275) and 6 hub genes (THBS1, IFNAR2, ARHGAP5, TUBB2B, FLNC, and NTF3) for osteoporosis." (PMID 35757478, 2022).
Salmonella Infections (1 paper, 2024). Infections with bacteria of the genus SALMONELLA. "The KEGG pathway analysis identified two significant pathways, namely Salmonella infection and intercellular junction, involving the RIPK1 and TUBB2B genes." (PMID 39682314, 2024).
schizophrenia (1 paper, 2023). A major psychotic disorder characterized by abnormalities in the perception or expression of reality. "Abnormalities in β-microtubulin (Tubb2b) have been suggested to be probably associated with the pathophysiology of schizophrenia and have a unique role in neuronal differentiation and cell viability." (PMID 37362918, 2023). "In patients with schizophrenia, Tubb2b protein expression is reduced in the anterior cingulate cortex and increased in the dorsolateral prefrontal cortex; however, it remains unchanged in the superior temporal gyrus or hippocampus." (PMID 37362918, 2023).
somatotropinomas (1 paper, 2018). "In particular, TUBB2B was found significantly downregulated in AIPmut positive (−8.3-fold change, P = 0.0043) and AIPmut negative (−5.2-fold change, P = 0.0464) somatotropinomas, compared with the normal pituitaries." (PMID 29507682, 2018).
triple-negative breast carcinoma (1 paper, 2025). An invasive breast carcinoma which is negative for expression of estrogen receptor (ER), progesterone receptor (PR), and human epidermal growth factor receptor 2 (HER2). "Tubulin beta 2B class IIb (TUBB2B), a β-tubulin isoform regulating axon guidance during embryonic development, was found to be overexpressed in various types of cancers including triple-negative breast cancer (TNBC)." (PMID 39962586, 2025).
urothelial carcinoma (1 paper, 2023). A malignant neoplasm derived from the transitional epithelium of the urinary tract (urinary bladder, ureter, urethra, or renal pelvis). "Additionally, TUBB2B was upregulated in tumors with high KMT9α expression (fold change 5.25; raw P = 8.54 × 10−4; adj P = 6.66 × 10−2), which is considered a marker of small-cell/neuroendocrine-like urothelial carcinoma." (PMID 36831256, 2023).
Ventriculomegaly (1 paper, 2021). An increase in size of the ventricular system of the brain. "In the TUBB2B cohort, agenesis of the olfactory bulb was significantly more prevalent in severely affected individuals while multifocal PMG, PMG-like CD, and ventriculomegaly were associated with a rather milder course of disease." (PMID 33082561, 2021).
West syndrome (1 paper, 2019). "Concerning epileptic clinical manifestation, West syndrome is the most frequent clinical phenotype at onset in patients carrying TUBA1A and TUBB2B gene mutations." (PMID 31269740, 2019).